GATA2 (GATA binding protein 2)
Diseases named in the same sentence as GATA2 in open-access papers (continued):
Sharing a sentence is not in itself a finding about the gene and the disease.
hematological malignancies (continued). "While this specific p.Arg396Trp variant has not been previously reported in any disease context, other pathogenic GATA2 mutations are well-documented in hematologic disorders, particularly GATA2 deficiency syndrome, where they typically disrupt zinc finger domain function and DNA binding capacity." (PMID 41154393, 2025). "Furthermore, GATA2 has well-documented roles in both immune function and hematological malignancies: autosomal dominant mutations in GATA2 can also lead to immunological disorders and hematologic malignancies." (PMID 31413257, 2019). "Accumulating lines of clinical evidence support the emerging hypothesis that loss-of-function mutations of GATA2 cause inherited hematopoietic diseases, including Emberger syndrome; dendritic cell, monocyte B and NK lymphoid (DCML) deficiency; and MonoMAC syndrome." (PMID 35440757, 2022). "Goal of this study was to determine the prevalence of GATA2 deficiency in children and adults with PAP and hematologic disorders." (PMID 26264606, 2015). "Any potential involvement of GATA2 downregulation in the development of haematological disorders remains as yet unclear." (PMID 21297973, 2011). "While the specific p.Arg396Trp variant has not been previously reported, pathogenic GATA2 mutations are well-characterized in hematologic malignancies, where they typically disrupt zinc finger domain function and DNA binding capacity." (PMID 41154393, 2025). "Notably, heterozygotes for germline P/LP variants in GATA2, ETV6, and RUNX1 (both cohorts), and DDX41 (UKBB only) have significantly increased risk for developing hematological malignancies." (PMID 39501104, 2025). "Pulmonary dysfunction is a common finding in up to 50% of patients with GATA2 deficiency, even in the absence of a hematopoietic disease." (PMID 41322420, 2025). "Nearly one-quarter (24.3%, 100/412) of the cohort had no symptoms associated with hematologic malignancies highlighting the incomplete penetrance of GATA2 predisposition." (PMID 34633564, 2021). "This question is unsolved mainly as Gata2 heterozygote mice do not develop hematologic malignancies." (PMID 34633564, 2021). "For example, in FA, revertant mosaicism in the blood may improve overall blood counts, but still confers a risk for leukemogenesis, while in the rare single cases of reversion in GATA2 deficiency and RUNX1-FPD, hematologic malignancies have not been reported." (PMID 35356204, 2022).
genetic disorder (11 papers, 2006 to 2025). "GATA2 deficiency is a rare genetic disorder associated with hematologic, infectious, and neoplastic complications." (PMID 39981594, 2025). "GATA2 deficiency is a rare genetic disorder caused by heterozygous mutations in the GATA2 gene, leading to haploinsufficiency and a broad spectrum of clinical manifestations." (PMID 41438140, 2025). "Identification of genetic disorders such as GATA2 deficiency is still important in the setting of malignancy; however, as identification is essential for improved counseling, treatment decisions, and prevention in family members." (PMID 39981594, 2025). "GATA2 deficiency is a rare genetic disorder caused by germline haploinsufficiency of a transcription factor essential for vascular development, hematopoietic stem cell maintenance, and immunity development." (PMID 40981111, 2025). "GATA2 deficiency is a rare genetic disorder stemming from haploinsufficiency of the GATA2 gene and represents a syndrome with heterogeneous clinical presentations." (PMID 39981594, 2025). "GATA2 deficiency is a rare genetic disorder resulting from heterozygous mutations in the GATA2 gene, a crucial transcription factor involved in hematopoiesis, immune function, and lymphatic development." (PMID 41438140, 2025). "Careful description of cohorts with GATA2 deficiency from different countries and genetic backgrounds will help to unravel the enormous heterogeneity of this recently discovered genetic disorder." (PMID 35273927, 2022). "Germline GATA2 mutations are involved in a group of complex syndromes with overlapping clinical features, including a rare genetic disorder called MonoMAC, Emberger syndrome and familial AML following MDS." (PMID 24754962, 2014). "The GATA2 genomic locus has been identified as conferring susceptibility to human genetic disease." (PMID 36806681, 2023). "Our work suggests that common variants within GATA2 play a role in CAD, an important complex genetic disease." (PMID 16934006, 2006). "This phenomenon of modifier genes has been well described in other genetic disorders and with increasing resources and expertise in computation and bioinformatics, the role of modifier genes affecting GATA2 function may help to explain the different EBV phenotypes observed with GATA2 deficiency." (PMID 29375553, 2017). "Furthermore, accumulating studies have demonstrated that GATA2 and GATA3 are involved in distinct types of inherited diseases as well as carcinogenesis in diverse tissues." (PMID 33803938, 2021).
adenocarcinoma (5 papers, 2009 to 2025). A common cancer characterized by the presence of malignant glandular cells. "Moreover, increased levels of GATA2 were associated with favorable LS and PFS in LC, especially in adenocarcinoma subtypes." (PMID 34093794, 2021). "Here we evidence Gata-2 and Gata-3 to be up to −12.7-fold down regulated in adenocarcinoma." (PMID 19812696, 2009).
infectious disease (4 papers, 2017 to 2025). A disorder directly resulting from the presence and activity of a microbial, viral, or parasitic agent in humans. "Following evaluation by an infectious disease specialist, genetic testing was advised, ultimately identifying a heterozygous GATA2 mutation (c.988C>T; p.Arg330)." (PMID 41438140, 2025). "GATA2 deficiency has been associated with a large number of diseases particularly hematologic and infectious diseases." (PMID 29375553, 2017). "While the myelodysplastic and infectious disease manifestations in patients with GATA2 deficiency have been well described, only a handful of case reports and case series have reported rheumatological manifestations in patients with GATA2 deficiency." (PMID 32433473, 2020). "Thus, additional studies of GATA2 should provide insights into the role of this gene in control of EBV and other infectious diseases." (PMID 29375553, 2017).
colorectal (2 papers, 2020 to 2025). "Given that GATA2 has been reported as an oncogene, GATA2 expression was increased in ZFP90 knockout HCT116 cells, and ZFP90 knockout blocked colorectal carcinogenesis, we chose BMP4 as the biological candidate target of ZFP90 for validation." (PMID 31641208, 2020).
hematological cancer (2 papers, 2014 to 2022). "An expression analysis in the 26 of the hematological cancer cell lines and 53 primary AML samples revealed GATA-2 and WT1/AWT1 co-expressed in 96% cases (51/56) consistent with this mechanism being a regulator of expression at the locus." (PMID 24405639, 2014).
inflammation (2 papers, 2024 to 2025). Aberrant reaction of the microcirculation characterized by movement of fluid and leukocytes from the blood into extravascular tissues. "These comprehensive analyses demonstrated that GATA2 directly upregulates genes associated with kidney inflammation." (PMID 40516868, 2025). "Accordingly, we hypothesized that GATA2 downregulation may disrupt the macrophage phagocytosis and aggravate pulmonary inflammation by enhancing the expression of pro-inflammatory cytokines in macrophages during COPD development." (PMID 39379099, 2024).
neurodegenerative disease (2 papers, 2022 to 2026). A disorder of the central nervous system characterized by gradual and progressive loss of neural tissue and neurologic function. "Specifically, IL4 and GATA2 are associated with oxidative phosphorylation and multiple neurodegenerative disease pathways, suggesting a potential synergistic or complementary role in energy metabolism and nerve cell function." (PMID 41481554, 2026).
psychiatric disorder (2 papers, 2022 to 2023). A disorder characterized by behavioral and/or psychological abnormalities, often accompanied by physical symptoms. "We have found GATA2, FOXC1 and TFAP2A among highly expressed TFs that are associated with DEGs are shared between PD and psychiatric disorders." (PMID 37654790, 2023).
head and neck tumors (1 paper, 2019). "Among the most impressive differences in TF activity, head and neck tumors display lower activities of FEV, TFAP2B and GATA2 and higher activities of TFEC, LEF1, and MAFB compared to SDHD-null tumors of other anatomical locations." (PMID 31234811, 2019).
neurological disorders (1 paper, 2024). "However, in the context of neurological disorders, an association between GATA2 and SETBP1 has not been reported." (PMID 39350244, 2024).
skin disorder (1 paper, 2025). Any deviation from the normal structure or function of the skin or subcutaneous tissue that is manifested by a characteristic set of symptoms and signs. "GATA2 deficiency should be considered in patients with IBD-like symptoms, refractory skin disorders, and hematological abnormalities." (PMID 40821825, 2025).
vasculopathy (1 paper, 2017). "Collectively, our study uncovered a novel molecular mechanism for GA pathogenesis and illustrated the important role of GATA2 and its SUMOylation in vasculopathy." (PMID 28569748, 2017). "Combining our present findings about GATA2 and IκBα SUMOylation in GA, it is very likely that the modulation of the SUMO system in a selective transcription factor network within the endothelium is critical in the molecular pathogenesis of vasculopathy." (PMID 28569748, 2017).
GATA2 also shares sentences with these, for which no sentence is quoted: deafness (6 papers); Shwachman-Diamond syndrome (6); pulmonary fibrosis (5); alveolar proteinosis (4); ataxia telangiectasia (4); bacterial infections (4); cardiovascular disease (4); platelet disorder (4); Wiskott-Aldrich syndrome (4); acute lymphoblastic leukaemia (3); asthma (3); chronic obstructive pulmonary disease (3); combined immunodeficiency (3); congenital neutropenia (3); epidermodysplasia verruciformis (3); hairy cell leukemia (3); hyper-IgE syndrome (3); Mycobacteriosis (3); Netherton syndrome (3); panniculitis (3); psoriasis (3); viral warts (3); acquired immunodeficiency syndrome (2); acute megakaryoblastic leukemia (2); bare lymphocyte syndrome (2); clear cell renal cell carcinoma (2); Diamond-Blackfan anemia (2); dyslipidemia (2); eczema (2); Kabuki syndrome (2).
A further 123 diseases each share a sentence with GATA2 in 2 papers or fewer.